MSH3 (mutS homolog 3)
Diseases named in the same sentence as MSH3 in open-access papers (continued):
Sharing a sentence is not in itself a finding about the gene and the disease.
cancer (continued). "Six non-BRCA carriers (11.11%) carried germline mutations in other cancer susceptibility genes, including five mutations in five homologous recombination repair (HRR) pathway genes (9.26%) and one mutation in MSH3 (1.85%)." (PMID 33194720, 2020). "In MSI tumours, the most frequently mutated known cancer genes were ACVR2A (9/9, 100%), MSH3 (5/9, 56%), FBXW7 (5/9, 56%), and BRAF (5/9, 56%)." (PMID 30894686, 2019). "T2 specific variants were enriched in the cancer metastasis signaling (P = 4.33E‐03) including the matrix metalloproteases 11 (MMP11), low density lipoprotein receptor‐related protein 1(LRP1), mutS homolog 3 (MSH3), and son of sevenless homolog 2 (SOS2)." (PMID 30941903, 2019). "Moreover, MSH3 inactivation is primarily associated with instability of tetranucleotide repeats (EMAST) that has been frequently observed in moderately or poorly differentiated adenocarcinomas as well as in other cancers including lung, kidney, ovarian, and bladder cancer." (PMID 28250766, 2017). "Several notable genes with a known role in cancer were identified in our candidate gene set (e.g. Msh3, Kit, Fas)." (PMID 27480531, 2016). "The KEGG database brings up two signal pathways related to cancer development in humans (hsa05200, hsa05210) with Msh3 involved." (PMID 25079915, 2014). "In this study, we determined the impact of MSH3 on cytotoxicity induced by anti-cancer drugs used for CRC treatment." (PMID 23724141, 2013). "The powers to detect the observed effect sizes in tobacco-smoking cases of Mixed Ancestry group remained sufficient for MSH3 rs26279 (97.53%) and MLH3 rs28756991 (85.05%), whereas borderline association of PMS1 rs5742938 with cancer was underpowered at 64.06%." (PMID 22623965, 2012). "Available evidence for MSH3, although limited, suggests no increased risk of cancer in MSH3 heterozygotes." (PMID 40237887, 2025). "The role of the MSH3 gene in the pathogenesis of cancer was first explained by Benachenhou and coworkers when they demonstrated that mutation in hMSH3 may be involved in tumorigenesis." (PMID 39003369, 2024). "In humans, heterozygous mutations in MSH3 do not present a clear increased risk of cancer while biallelic loss-of-function or predicted loss-of-function mutations are associated with familial colorectal adenomatous polyposis." (PMID 38267530, 2024). "This highly specific role of MSH3 in MMR explains its limited association in cancers, with no known relationship to CNS-derived tumors being reported." (PMID 37177784, 2023).
cancer (continued). "On the other hand, increased Msh3 expression can result in an increase of harmful expansions but could potentially protect against cancer." (PMID 37127331, 2023). "Our phylogenetic inference analysis showed that the genes ATF7IP and MSH3 could participate in a tumor transition ending in aggressive entities or even carcinomas." (PMID 35563252, 2022). "Notably, two of these patients harbored heterozygous alterations in cancer predisposing genes associated with autosomal recessive cancer predisposition syndromes (NTHL1 and MSH3)." (PMID 33466343, 2021). "Rather, evidence suggests that MSH3 and its biomarker EMAST may be associated with modification of cancer behavior compared to initiating it." (PMID 25836926, 2015). "There is evidence that the approach to patient therapy for cancer may need to be modified as a result of MSH3 dysfunction, but this needs to be tested in a patient population rather than cells in culture." (PMID 25836926, 2015). "However, several studies showed association of other SNPs in MSH3 and MSH6 genes in different cancers." (PMID 23437280, 2013). "We determined the effect of MSH3 expression upon cell viability in response to anti-cancer drugs including SN-38, the primary metabolite of the topoisomerase I inhibitor irinotecan, the alkylating and DNA intercalating agent oxaliplatin, and the nucleoside analogue 5-fluorouracil (5-FU)." (PMID 23724141, 2013). "MSH3-deficient cancer cells maintain higher levels of phosphorylated histone H2AX and 53BP1 after oxaliplatin treatment in comparison with MSH3-proficient cells, suggesting that MSH3 plays an important role in repairing DNA double strand breaks (DSBs)." (PMID 23209772, 2012). "In mice, Msh3 deficiency alone did not cause cancer predisposition, but a simultaneous loss of Msh3 and Msh6 accelerated intestinal tumorigenesis while lymphomagenesis was not affected." (PMID 23209772, 2012). "Importantly, di-valent siRNAs show limited accumulation in liver and kidney and no detectable presence in the colon, a tissue in which MSH3 silencing is associated with cancer." (PMID 37177784, 2023). "Furthermore, Msh3 is significantly enriched in cancer pathways, which further supports the hypothesis that this mutation is important for the GASH/Sal phenotype." (PMID 32168507, 2020). "It is currently controversial whether EMAST is associated with oncogenic properties in humans, specifically as cancer development in Msh3-deficient mice is not enhanced." (PMID 23209772, 2012). "Promoter hypermethylation and mutational silencing of HR and MMR genes, such as RB, BRCA1/2, PTEN, MLH1, MSH3, MSH6 have been identified in human cancer." (PMID 36076047, 2022). "The lowest level of MSH3 mRNA expression is seen in a subset of diploid tumours, including some MSI-H cancers." (PMID 34298744, 2021). "In this context, IL-6 signaling drives the compartmental translocation of MSH3 and the EMAST cancer phenotype." (PMID 33923292, 2021). "MSH3, MSH6, APC and PIK3CA genes seem to play a bigger role in the path to cancer in this population." (PMID 28002797, 2017). "Further, rare mutations in MSH3 and FAN1 are known to cause rare forms of cancer, although they do not primarily affect the central nervous system." (PMID 39801710, 2025). "In the mentioned pan-cancer study that included 11,081 patients, 12 carried monoallelic PVs in MSH3, a similar frequency observed in gnomAD non-Finnish European controls." (PMID 40237887, 2025). "Taken together, we believe that MSH3 can be a key marker for predicting the prognosis of RCC and hope to add to the research on the immune microenvironment, immunotherapy, function, and pathway related to cancer." (PMID 37426643, 2023).
cancer (continued). "Due to the dual function of MSH3 in both MMR and HR, EMAST/MSI-L cancers could be potentially responsive to therapies that exploit the concept of synthetic lethality." (PMID 34298744, 2021). "To determine whether MSH3 is involved in DNA DSB repair, we determined the effect of anti-cancer drug treatment upon expression of the DSBs markers, phosphorylated histone H2AX (pH2AX) and Checkpoint kinase 2 (pChk2)." (PMID 23724141, 2013). "Mutations in the MSI target genes IGF2R and BAX were found in one (33.3%) and two (66.7%) out of the three rectal MSI-H carcinomas, respectively, whereas no mutations were detected in TGFBR2, MSH3, and MSH6 microsatellite sequences in this test series." (PMID 20979647, 2010). "Although this phenomenon has largely been seen among cancers that have surrounding inflammation as a source of IL-6, we have previously reported absence of MSH3 expression within the epithelium of hamartomatous polyps, which contain inflammation but are not neoplastic." (PMID 31789935, 2019). "Interestingly, we did not detect any mutation in TGFBR2, MSH3, or MSH6 microsatellite sequences in rectal or sigmoid MSI-H carcinomas in our test series." (PMID 20979647, 2010). "In addition, while mutations in MSH3 and MLH3 have been implicated in a variety of cancers and cancer predisposition syndromes, PMS1 mutations have not been definitively associated with any cancer predisposition to date either in mice or humans (see omim.org/entry/600258?search=pms1&highlight=pms1)." (PMID 32589669, 2020). "While J21 cells are a sub-clone of a cancer cell line (HT1080) with known defects in DNA repair genes (e.g. ERCC5, FANCC, MSH3, and WRN), hTERTs are an immortalized, non-cancerous cell line that does not contain any known defects." (PMID 25893404, 2015).
tumor (89 papers, 1998 to 2026). "There existed however CC patients, who also had a higher mutational burden, in six such cases five carried a tumor with a MSH3 mutation and one with MLH1 mutation." (PMID 41420192, 2025). "Both germline MSH3 variants were confirmed by Sanger sequencing of the PCR product generated from patient’s normal colon and tumor tissue DNA." (PMID 38243056, 2024). "Nevertheless, changes in the MSH3 exon 1 polymorphism genotype were observed in tumor tissue compared to the corresponding normal mucosa, manifesting as loss of heterozygosity (LOH), which was observed in 27.4% (26/95) of the informative samples." (PMID 39199686, 2024). "WES after LCM confirmed that tumor regions carrying frameshift mutations in either the MSH6 or MSH3 homopolymer had significantly increased SNV, InDel and overall mutation burden." (PMID 38956208, 2024). "Strong cytoplasmic and membrane-bound MSH3 signals were detected in some cells in both the tumor and normal colon tissues, suggesting that variant MSH3 accumulates in cytoplasm/membrane." (PMID 38243056, 2024). "A statistically significant positive correlation was found between MSH3 mutation and tumor diameter (P < .05)." (PMID 37737217, 2023). "The number of patients with a tumor diameter of more than 4.35 cm was 37 (50.7%), and the MSH3 mutation was present in 10 of them (27%)." (PMID 37737217, 2023). "But is the loss of nuclear MSH3 staining due to its translocation to the cytosol observed in clinical tumor samples?" (PMID 37510378, 2023). "In the context of MMR, reduction, or complete loss of nuclear MSH3 expression has been associated with the presence of EMAST in tumor cells." (PMID 37510378, 2023). "Based on these observations, the effect of checkpoint blockade in MSH3-deficient tumours is difficult to predict." (PMID 34843512, 2021). "The specific aim of the present molecular profiling study was to identify potential driver genes of tumourigenesis in the only currently known form of human neoplasia to be caused by biallelic pathogenic MSH3 germline variants." (PMID 34843512, 2021). "In our cohort, 4 patients were carriers of monoallelic predicted pathogenic variants in EXO1 or MSH3 genes, and one MSH3 carrier case harbored a tumor showing EMAST." (PMID 32635641, 2020). "Msh3 expression was obviously lost in tumor tissue samples of two patients with MSH3 mutation and studies have suggested that deficient MMR protein expression in tumor tissues were implications for the present of MMR gene mutations." (PMID 25927356, 2015). "In total, six paired (normal and tumor) breast tissue samples, one paired colon tissue sample and one paired ovarian tissue sample from three families with MSH3 mutations were available for MSI and IHC analysis." (PMID 25927356, 2015). "It is therefore possible that the MSH3 association is confined to patients with tumours belonging to specific DLBCL subgroups." (PMID 24098683, 2013). "Here, we describe the identification of HLA-A0201-restricted CTL epitopes generated by a MSI+ tumor specific frameshift mutation in a cMS of the MSH3 gene." (PMID 22110587, 2011). "Recently, EMAST and also low dinucleotide repeat instability have been associated with MSH3 deficiency both in tumour cell lines and in sporadic colorectal tumours." (PMID 20160730, 2010). "EMAST is characteristic of tumours that develop in the context of MSH3-associated polyposis." (PMID 40237887, 2025). "Its presence is often associated with MSH3 dysfunction and chronic inflammation, and it may influence tumor behavior and responses to immunotherapy." (PMID 40709993, 2025). "MSH3 encoded by four of the variants, including c.1148delA, c.2319-1 G > A, c.2760delC, and c.3001-2AC, was undetectable in either the nucleus or cytoplasm of normal colon and tumor cells by IHC staining." (PMID 38243056, 2024).
tumor (continued). "To determine functionality of the observed compound heterozygous MSH3 variants in tumor vs normal tissue, we examined instability of the microsatellites with mono- and dinucleotide repeats and that of elevated microsatellite alterations at selected tetranucleotide repeats (EMAST) markers." (PMID 38243056, 2024). "Furthermore, variant MSH3 protein was detected in the cytoplasm and cell membrane in the normal and tumor cells." (PMID 38243056, 2024). "Also, MSH3 was closely associated with tumor microenvironment infiltration, immune checkpoint genes, and immunotherapy sensitivity." (PMID 37426643, 2023). "Furthermore, we found co-mutation with MSH3 across the tumours underlying each model, ranging from 20% (SRCAP) to 33% (BMPR2) of the mutated tumours." (PMID 36883553, 2023). "This correlation suggests that all eight models relate to a genome-instability phenotype, which may be driven by the MSH3 co-mutated tumours or, potentially, a concurrent deficiency of other genes within the MMR system." (PMID 36883553, 2023). "However, combining the tumours with reduced and moderate expression into one group, a significant association of lower MSH3 expression with EMAST (2+) and (3+) was found." (PMID 35099128, 2022). "Interestingly, overexpression of MSH3, which can also occur in the tumour, causes substantial changes in the levels of MutSα and MutSβ complexes." (PMID 32756484, 2020). "In keeping with this, tumor formation rarely arises as a consequence of loss of only Msh6 or Msh3." (PMID 23821616, 2013). "Therefore, mutated MSH3 shows several characteristics an ideal tumor antigen should have and thus constitutes another important candidate for the development of immune-based MSI+ tumor targeting strategies." (PMID 22110587, 2011). "MC38 reflect MSI-H tumours containing a mutation in the MSH3 genes, whilst CT26 reflect MSS tumours containing a KrasG12D mutation." (PMID 41463180, 2025). "Loss of nuclear MSH3 explains the observed genetic instability, MSI-L/EMAST, found enhanced in tumor tissues." (PMID 38243056, 2024). "The impact of the MSH3 Ala1045Thr and MSH6 557G > T variants on various clinicopathological parameters, such as stage, tumor extension, lymph node invasion, and metastasis, was assessed." (PMID 39003369, 2024). "We also investigated the role of MSH3 Ala1045Thr and MSH6 557G > T polymorphism based on clinical-pathological features such as stage, tumour size, lymph node invasion and metastasis." (PMID 39003369, 2024). "Given that the inflammatory tumor microenvironment contains free oxygen radicals from oxidative stress and pro-inflammatory cytokines, follow-up studies have suggested that these factors might be the main drivers of the inflammation-driven loss of nuclear MSH3." (PMID 37510378, 2023). "Since the proposed mechanism of MSH3 inactivation is by its nature probably reversible, as suggested by the existence of nuclear localization and export signals, the change in MSH3 localization might be long gone by the time the tumor sample is collected, even though the damage it causes remains." (PMID 37510378, 2023). "Considering the EMAST (2+) category, 23 of 86 (26.7%) tumours with reduced/moderate expression compared to 70 of 402 (17.4%) tumours with strong MSH3 expression were EMAST (2+) positive (p = 0.046)." (PMID 35099128, 2022).